PBRM1 (polybromo 1)
Diseases named in the same sentence as PBRM1 in open-access papers (continued):
Sharing a sentence is not in itself a finding about the gene and the disease.
tumor (continued). "In addition, PBRM1 mutations were found to enhance T‐cell‐mediated killing of tumor cells in an unbiased, high‐throughput screen in a melanoma model." (PMID 30585695, 2019). "However, it is still not clear how critical H3K14ac recognition is to PBRM1's association with the chromatin and how mutant PBRM1 impacts tumor growth in a mouse model." (PMID 30585695, 2019). "Regardless of whether the patient has co-occurring VHL and BAP1 mutations or co-occurring VHL and PBRM1 mutations, T cell activation genes form coordinated co-expression in the tumor." (PMID 30814637, 2019). "Using mouse xenograft models, we tested whether the PBRM1 BD mutations abrogate its tumor suppressor function." (PMID 30585695, 2019). "Altogether, it seems that PBRM1 mutations are associated with specific molecular tumor expression profiles, and that they may have a predictive role." (PMID 31861590, 2019). "Alternatively, tumor heterogeneity or sampling issues may account for these PBRM1 mutations seen only in the post-treatment samples." (PMID 30256787, 2018). "As PBRM1 suppression led to reduced ISGF3 expression and activity and enhanced tumor growth (data not shown), we asked whether ISGF3 over-expression reverses the enhanced tumor growth elicited by PBRM1 deficiency." (PMID 30355451, 2018). "Conversely, reactivation of ISGF3 retards tumor growth by PBRM1-deficient ccRCC cells." (PMID 30355451, 2018). "In the case of PBRM1, the loss frequencies increased with stage and the associations between truncal loss groups with high stage had much smaller p values than that of Loss in Tumor (Total), which suggested higher confidence." (PMID 28445125, 2017). "Yet, PBRM1 mutations seem to be associated with poor patient outcome in these tumours, suggesting that PBRM1 may modulate the probability of RCC cells acquiring metastatic traits at a later stage of tumour progression." (PMID 27756687, 2017). "Furthermore, mutations in PBRM1 are identified as the root of tumor evolution in a subgroup of ccRCC." (PMID 27556922, 2016). "Using xenograft analysis, we provide evidence suggesting that ARID1A loss might be more potent in enhancing tumor growth than PBRM1 loss." (PMID 27764136, 2016). "Concerning the prognostic significance of BAP1, PBRM1 and SETD2 mutational status, BAP1 loss correlates with high Fuhrman nuclear grade and mTORC1 activation, higher tumor stage, and worst overall survival, while PBRM1 mutations seem to identify a favorable group of ccRCC." (PMID 26452128, 2015). "PBRM1 protein expression was positively associated with tumor stage and tumor grade." (PMID 25978027, 2015). "Additionally, RNA sequencing data identified pathways that could explain how Pbrm1 loss contributes to tumor formation in a Vhl-deficient model." (PMID 41602827, 2026). "Notably, co-mutations with PBRM1, a tumor suppressor, enhance ICI efficacy in POLD1-mutated tumors." (PMID 40661943, 2025). "However, the consequences of BAP1 and PBRM1 mutations on overall tumor cell chromatin accessibility and associated transcriptome changes in ccRCC are largely unknown." (PMID 36973268, 2023). "Interestingly, in a small percentage of patients, BAP1 and PBRM1 mutations may coexist and in these cases, the resulting neoplasm manifests rhabdoid features." (PMID 37887570, 2023). "Loss of this positive gene regulation, either by suppression or mutation of PBRM1, appears to support the expression of genes that are critical for cancer functions including hypoxia-dependent growth and survival, bypass of cell-cycle checkpoints, and aberrant adhesion that promotes tumor expansion." (PMID 37394010, 2023). "However, the underlying mechanism of how PBRM1 mutation promotes tumorigenesis and tumor progression remains unclear." (PMID 34535962, 2021).
tumor (continued). "The frequency of PBRM1 mutation was similar between patients with aggressive and non-aggressive ccRCC, perhaps because it is an early, essential event in tumorigenesis that does not impact clinical outcome, but instead plays a principal role in tumor initiation." (PMID 31963294, 2020). "Notably, very few homozygous deletions or mutations of HAMPs (except for PBRM1) were observed in cancer, suggesting that HAMPs may be essential for tumor growth, and that complete loss may be lethal." (PMID 30760718, 2019). "How mutations in the gene PBRM1 promote carcinogenesis and tumor progression is still unknown." (PMID 31861590, 2019). "In addition, tumor‐derived mutations in BD2 resulted in reduced recognition of H3K14ac by PBRM1." (PMID 30585695, 2019). "However, the biological consequences of PBRM1 somatic mutations (e.g., truncated mutations) that drive tumor progression in ccRCC remain unclear." (PMID 27556922, 2016). "However, PBRM1 was also a ubiquitous mutation in 20–30% of ccRCC tumours analysed." (PMID 26448938, 2015). "During tumor progression, PBRM1 directly regulates vimentin expression, and PBRM1 deletion results in the activation of the EMT and subsequent metastasis." (PMID 40454484, 2025). "TIMER database analysis also showed that the infiltration abundance of immune cells, such as CD8+ T cells, neutrophils, and dendritic cells, in the tumor mesenchyme was negatively correlated with PBRM1 expression." (PMID 40093909, 2025). "To investigate the role of macrophages in PBRM1 knockdown‐mediated enhancement of immunotherapeutic effects, we utilized clodronate liposomes to deplete tumor‐infiltrating macrophages and assessed tumor volume and burden." (PMID 39656940, 2025). "PBRM1 ablation in established PDAC results in the conversion of tumor grade into poorly differentiated PDAC in mice." (PMID 40454484, 2025). "The VHL gene primarily affects tumor development by regulating the hypoxia response, whereas the PBRM1 gene contributes to tumor development through chromatin remodeling and immune regulation." (PMID 40969770, 2025). "Our data established PBRM1 as a tumor suppressor that controls tumor grade and metastasis of PDAC by regulating vimentin expression." (PMID 40454484, 2025). "The heightened expression of PBRM1 induces by the nanomedicine substantially inhibited tumor growth in iCCA." (PMID 39823528, 2025). "In this study, we demonstrated for what we believe to be the first time that PBRM1 is a critical determinant of tumor grade, EMT, and metastasis in PDAC and functions by directly downregulating vimentin expression." (PMID 40454484, 2025). "We discuss potential molecular mechanisms underlying this transformation, with mutations in NF1, PBRM1, and FAT1 likely contributing to the tumor's atypical morphology and loss of melanocytic markers." (PMID 40125165, 2025). "Collectively, our results suggest that PBRM1 plays a tumor‐suppressive role in the onset and progression of iCCA." (PMID 39823528, 2025). "Further evaluation of the tumor by Caris Molecular Intelligence revealed several mutations, including the NF1 variant of uncertain significance (VUS), NRAS, PBRM1, FAT1, TERT Promoter, and ATM." (PMID 40125165, 2025). "Clinically, this implies that while LST1 reflects chronic inflammatory activation, it achieves greater diagnostic discrimination when combined with tumor-specific markers such as CA9, PBRM1, and HLA-exhaustion signatures." (PMID 41488617, 2025). "TIMER database analysis showed that PBRM1 expression was correlated with tumor mesenchymal lymphocyte infiltration." (PMID 40093909, 2025). "We demonstrated that the PBRM1/vimentin axis is a critical regulator of tumor grade and metastasis in both mouse and human PDAC." (PMID 40454484, 2025). "We examined the chromosome accessibility of tumor cells by ATAC-Sequence and found that the central peak of PBRM1-deficient CRC cells increased compared with the control group." (PMID 40093909, 2025).
tumor (continued). "The loss of PBRM1 was noted to lead to increased HIF transcription, STAT3, and mTOR signaling, thereby favoring tumor growth." (PMID 40725144, 2025). "PBRM1 exerts an anti‐tumor effect by inhibiting the activity of the ERK1/2 and JNK/c‐Jun pathways, and the effect is blocked by ERK1/2 inhibition." (PMID 39823528, 2025). "Our findings demonstrate that Pbrm1 knockdown suppressed tumor growth and improved survival rates when combined with PD‐1 monoclonal antibody treatment." (PMID 39656940, 2025). "For subgroup analysis by genetic mutations, the CDX model with BAP1 mutations exhibited the most rapid tumor growth rate, compared with the models with VHL, PBRM1, and SETD2 mutations (P < 0.01)." (PMID 40856833, 2025). "Our case had polybromo-1 (PBRM1) and BAP1 functional loss, tumor mutational burden of 4 Muts/Mb, stable microsatellite status, and a PD-L1 tumor proportion score of <1%." (PMID 41199851, 2025). "Our study further validated that PB1‐p62 improves immune efficacy by increasing the infiltration of M1 macrophages and T cells, which prolonged the survival of PBRM1 wild‐type tumor‐bearing mice." (PMID 39656940, 2025). "In conclusion, we demonstrated that PBRM1 is a critical determinant of tumor grade and metastasis in PDAC and functions by directly regulating vimentin expression." (PMID 40454484, 2025). "In contrast, despite the fact the PBRM1-deficient tumours grow more slowly than the parental B16 tumours, survival was further improved following Mps1 inhibitor treatment in mice bearing the PBRM1 KO derived tumours." (PMID 40011561, 2025). "This patient’s tumor had a truncation in the polybromo-1 (PBRM1) gene, which is a tumor suppressor gene involved in the control of the cell cycle, the promotion of genomic stability, and centromeric cohesion." (PMID 41199851, 2025). "Data from the Gene Expression Omnibus (GEO) database (GSE76297) demonstrated a significant reduction in PBRM1 messenger (mRNA) expression in tumor tissues compared to their matched non‐tumoral tissues." (PMID 39823528, 2025). "We have previously shown that two genes that are frequently mutated in ccRCC, PBRM1 (50%) and BAP1 (15%), are associated with tumor grade and aggressiveness." (PMID 40097393, 2025). "The patient's tumor demonstrated mutations in VHL, PBRM1, and SETD2, which are commonly associated with clear cell RCC and have significant implications for tumor behavior and therapy selection." (PMID 40600205, 2025). "The genes BAP1 and PBRM1 expression on the 3p chromosome are mentioned as being frequently deleted in ccRCC and as an independent predictor of tumor recurrence." (PMID 41479787, 2025). "Taken together, the results suggest that the E27 inclusion in PBRM1 contributes to tumour progression." (PMID 39375538, 2024). "Overall, the results suggested that the E27-included isoform of PBRM1 promotes PD-L1 expression in ccRCC cancer tissues and suppresses the tumour-killing activity of immune cells." (PMID 39375538, 2024). "In several cancers, notably ccRCC, PBRM1 functions as a tumor suppressor, inhibiting malignant tumor transformation and growth." (PMID 38371625, 2024). "At 9 days post-injection, the E27 exclusion in Pbrm1 by PBRM1 SSO transfection significantly reduced the tumour volume (Fig. EV4E,F)." (PMID 39375538, 2024). "Ageing process was represented by associations with cellular mitotic clocks such as epiTOC2, SBS1, telomere length, and PBRM1 and SETD2 mutations, which ticked faster as tumours progressed." (PMID 39592856, 2024). "At the same time, mutations in PBRM1 and BAP1, the drivers of tumor evolution, also showed significant differences in our subtypes." (PMID 39513109, 2024). "Transfection of PBRM1 SSO into various cancer cell lines not only promoted E27 exclusion in PBRM1 but also reduced cancer cell resistance to NK-92 cell-mediated tumour-killing activity (Fig. EV4C)." (PMID 39375538, 2024).
tumor (continued). "Although PBRM1 is often classified as a tumor suppressor, clinical observations correlating PBRM1 protein expression or mutational status with ICB and antiangiogenic response suggest that PBRM1 plays diverse roles in cancer." (PMID 38460939, 2024). "These tumours have alterations in chromosomal numbers and are associated with mutations in MET, CDKN2A, SETD2, BAP1, PBRM1, NFE2L2, and mTOR genes and have a better prognosis when compared with clear cell RCC in the organ-confined stage." (PMID 38265103, 2024). "Secondary to VHL, additional mutations (most notably in PBRM1, BAP1, and SETD2) enlist a large number of genetic and epigenetic events to drive advanced tumor evolution." (PMID 38618956, 2024). "As a putative tumor suppressor in several cancers, PBRM1 protein expression is often abrogated by truncations and deletions." (PMID 38460939, 2024). "Mutations in PBRM1 and SETD2 often co-exist while mutations in PBRM1 and BAP1 seem mutually exclusive at the clone level, with distinct tumor phenotypes." (PMID 37999735, 2024). "Studies have shown that PBRM1 not only plays a critical role in preventing tumor development, but also participates in regulating genes implicated in the DNA damage response and maintaining redox equilibrium." (PMID 38365747, 2024). "EBV-miR-BART11 and EBV-miR-BART17-3p inhibit FOXP1 and PBRM1, respectively, and enhance the transcription of PD-L1, thus promoting tumor immune escape." (PMID 38428879, 2024). "Recently, it has been shown that multiple subclonal drivers including PBRM1, SETD2, or BAP1 mutations contribute to high genetic intra-tumor diversity in ccRCC and impact on clinical outcomes." (PMID 37999735, 2024). "BAP1 and PBRM1 gene expression, both on chromosome 3p, independently predict tumor recurrence, with BAP1-mutant tumors indicating worse outcomes." (PMID 38730649, 2024). "In other tumor models, mutations in the SWI/SNF chromatin remodeling complex, including PBRM1 and ARID2, have been found to sensitize tumor cells to T-cell-mediated killing." (PMID 38653864, 2024). "Next, we investigated the pathway and tumor microenvironment differences between POL&PBRM1 and others." (PMID 39218995, 2024). "PBRM1 is a bona fide tumor suppressor in ccRCC in the context of VHL deletion; however, in other cancer contexts, it is oncogenic and a proposed therapeutic target." (PMID 36808431, 2023). "A recent analysis pointed out that the combination of PBRM1 status and tumor-infiltrating lymphocyte density allows us to obtain a trustworthy prognostic model for ccRCC." (PMID 37887570, 2023). "Other driving mutations, including SETD2, PBRM1 and BAP1, lead to genomic instability and promote tumor cell metastasis through the disorder of various metabolic and immune response pathways." (PMID 36966163, 2023). "Mutations in PBRM1 and BAP1 are also critical driver events of ccRCC tumor development and are known to be prognostic for outcomes in RCC." (PMID 37173966, 2023). "Polybromo 1 is a protein encoded by PBRM1 and is involved in the PBAF complex (an SWI/SNF chromatin remodeling complex) known for its tumor suppressor role." (PMID 37887570, 2023). "Analysis of TNBC tumors corroborated that (i) MUC1 and PBRM1 are associated with decreased responsiveness to chemotherapy and (ii) MUC1-C expression is associated with the depletion of tumor-infiltrating lymphocytes (TIL)." (PMID 36445328, 2023). "It was demonstrated that defects in the PBAF-specific subunit (PBRM1) can also contribute to the state of synthetic lethality of tumor cells when using PARP inhibitors." (PMID 37175555, 2023).
tumor (continued). "Although mutation or inactivation of the Von Hippel-Lindau (VHL) tumor-suppressor gene is considered the hallmark of ccRCC, the second most mutated gene after VHL is PBRM1." (PMID 36674417, 2023). "The list of potential tumor suppressor hits included both known factors, such as Ezh2 and Tle4, as well as novel candidates, including Kdm5c, Pcgf3, Chd1 and Pbrm1." (PMID 36631623, 2023). "WB analyses of tumor tissues revealed that Fdcyd treatment significantly induced γH2AX levels, as well as PARP1 cleavage in PBRM1-deficient 786-O tumors." (PMID 35719970, 2022). "We also observed somatic mutations in other RCC‐associated genes, such as PBRM1 and AHNAK2, most of which were conserved between RCC organoids and the corresponding tumour tissues." (PMID 35802820, 2022). "Our above studies have shown that c‐JUN activation was involved in the tumour‐promoting effect of PBRM1 in HUTU‐80 cells." (PMID 36178086, 2022). "A second benefit of targeting ARID1A is the recent demonstration that inactivation of certain SWI/SNF chromatin remodelling complex subunits (i.e. ARID1A and PBRM1) renders tumours more likely to respond to ICIs32,46." (PMID 35393414, 2022). "FOXP1 establishes interactions with the PBAF subtype to which PBRM1 belongs, binds to the PD-L1 enhancer, and promotes PD-L1 transcription, resulting in tumor immune escape." (PMID 35165282, 2022). "In the multivariable-adjusted results (model 2) that included patient clinical characteristics (tumour grade, size and stage), the association became stronger [HR (95% CI), VHL = 0.33 (0.14–0.79), PBRM1 = 0.25 (0.08–0.79)]." (PMID 35444164, 2022). "PBRM1-defective tumor cells exhibited elevated levels of DNA damage response and PARP inhibitor exposure exacerbated this phenotype." (PMID 35719970, 2022). "According to the results of tumor mutational burden analysis, VHL and PBRM1 made up the majority of the mutations." (PMID 36035192, 2022). "Mutation of PBRM1 (p = 0.0003) and mutation of mTOR (p = 0.005) were also associated with increased HIF metagene scores in this tumor type, consistent with previous findings." (PMID 36384128, 2022). "In humans, the VHL gene is located next to other tumor suppressors (e.g., PBRM1, BAP1 and SETD2) on chromosome 3p." (PMID 35463327, 2022). "The tumour suppressor genes SETD2 and PBRM1 were the most frequently mutated genes in our cohort (mutated in 62% and 57% of the patients, respectively)." (PMID 35231161, 2022). "There is little knowledge about how PBRM1 immunohistochemical expression correlates with the histomorphological features of ccRCC and the endothelial expression of tumor vasculature." (PMID 35205810, 2022). "PBRM1 is a tumor suppressor gene in many cancer types, is involved in regulating tumor immune function, and plays an important role in tumor immunity." (PMID 36456601, 2022). "PBRM1 knockdown resulted in decreased immunosuppressive cytokines, and PBRM1 levels in tumor tissues were negatively correlated with CD8 cytotoxic T-cell (CTC) infiltration." (PMID 35928964, 2022). "Additional driver mutations (SETD2, PBRM1, BAP1, and others) promote genomic instability and tumor cell metastasis through the dysregulation of various metabolic and immune-response pathways." (PMID 36428521, 2022). "However, the association of the PBRM1 immunohistochemical expression with histomorphological features of ccRCC and the endothelial expression of tumor vasculature, which is an important role of the tumor microenvironment related to treatment response, is little known." (PMID 35205810, 2022). "The expression level of FDX1 in ccRCC samples with different ages, gender, pathological tumor stage, histological tumor grade, VHL mutation, and PBRM1 mutation was analyzed." (PMID 36292610, 2022).